NRF1 (nuclear respiratory factor 1)
Diseases named in the same sentence as NRF1 in open-access papers (continued):
Sharing a sentence is not in itself a finding about the gene and the disease.
cancer (100 papers, 2009 to 2026). A tumor composed of atypical neoplastic, often pleomorphic cells that invade other tissues. "In conclusion, our findings reveal that NRF1 is a dominant cause of EZH2 overexpression in human cancers and that NRF1 overexpression increases the sensitivity of cancer cells to EZH2is." (PMID 42140904, 2026). "NRF1 works in cell homeostasis through transcriptional control mechanisms and has previously been implicated in multiple types of cancer." (PMID 34791179, 2022). "Under conditions of high glycolytic and glutaminolysis activities, such as those prevalent in cancer cells, NRF1 becomes O-GlcNAcylated, which disrupts its association with β-TrCP, leading to NRF1 stabilization." (PMID 34356615, 2021). "The NFE2L1 (also referred to as NRF1) protein has been implicated in cancer development, and degenerative, and metabolic disorders." (PMID 32316228, 2020). "NRF-1 degradation induced by hypoxia promotes some cancer cells becoming more susceptible to apoptosis: this interesting observation deserves further study." (PMID 31600993, 2019). "Taken together, these observations strongly suggest that the increase in MED28 expression by E2F-1, ETS-1, C/EBPβ, and NRF-1 is associated with cancer progression and poor prognosis." (PMID 30970566, 2019). "Taken together, it is inferable that Nrf1 deficiency results in constitutive activation and/or repression of putative Wnt/β-catenin-dependent and Wnt/β-catenin-independent signaling cascades in cancer development and malignant progression." (PMID 32273945, 2020). "In addition to controlling mitochondrial biogenesis, by activating or repressing the cancer hall mark genes, NRF1 may play a critical role in the acquisition of human cancer hallmark features." (PMID 30486409, 2018). "Before cancer development, the Nrf1-/- livers also exhibited interrelated steatosis, apoptosis, necrosis, inflammation and fibrosis." (PMID 40703332, 2025). "In silico studies exploring the apoptotic potential of BS have centered on NRF1, a key cancer cell survival protein." (PMID 41438988, 2025). "Tissue-specific knockout studies have demonstrated that NRF1 is essential for maintaining liver function and contributes to the pathogenesis of steatohepatitis (fatty liver inflammation) and cancer." (PMID 40362294, 2025). "To validate predicted interactions of NRF-1 with CD47 promoter we first performed in-silico analysis of ChIP-seq datasets derived from different types of cancer." (PMID 39742254, 2024). "Using chromatin immunoprecipitation (ChIP) approaches along with the analysis of ChIP-Seq cancer datasets, we identified the transcription factor NRF-1 which binds at multiple sites within the proximal CD47 promoter region." (PMID 39742254, 2024). "Nrf1 is also a potential target for cancer therapies, as cancers often experience chronic proteotoxic stress that is countered by the ubiquitin-proteasome system (UPS)." (PMID 38991033, 2024). "NRF1 is not only activated by CREB but also activates multiple significant pathways in cancer, which suggests that NRF1 plays a central role in HCC progression." (PMID 37875967, 2023). "Significant efforts on various types of cancers have been made to characterize the extramitochondrial biological processes of NRF1." (PMID 35448958, 2022). "NRF1 is involved in cancer growth by regulating E2F1 transcriptionand also a valuable prognostic biomarker for LIHC." (PMID 35448958, 2022). "A more recent study suggests that DDI2 plays a pro-tumoral role by activating NRF1 and ultimately increasing the ability of cancer cells to degrade ubiquitinated proteins in a proteosome-dependent manner." (PMID 36232810, 2022). "NRF1 and NRF2 double-positive expression in cancer cells was associated with the improved patient probability of survival." (PMID 36359002, 2022).
cancer (continued). "In the present study, we demonstrated that NRF1 was correlated with tumour size and promoted cancer cell proliferation in LIHC." (PMID 35448958, 2022). "Upstream, NRF1 is a master inducer of the expression of nuclear encoded genes of mitochondrial respiratory complex subunits, and NRF1 activity has previously been reported to promote cancer metastasis." (PMID 36230841, 2022). "Density-based co-expression analysis demonstrated NRF1 and NRF2 double-positive expression in cancer cells is associated with improved overall survival." (PMID 36359002, 2022). "Signal transducer and activator of transcription 3 (STAT3) and nuclear factor erythroid 2 related factor-1 (NRF1) play central roles in maintaining the homeostasis of proteasomes in cancer cells." (PMID 35269802, 2022). "Based on these findings, STAT3 and NRF1 have been proposed as the most important transcription factors for maintaining the homeostasis of proteasomes in cancer cells." (PMID 35269802, 2022). "A density-based co-expression analysis was performed, which demonstrated a significant positive association between survival probability and NRF1 and NRF2 protein co-expression in cancer cells." (PMID 36359002, 2022). "PGC1α has been linked to radioresistance due to its role in the activation of many others transcription factors including nuclear respiratory factor 1 (NRF1) and 2 (NRF2) which, in turn, are linked to radiation response in cancer." (PMID 33069104, 2021). "As expected, the suppression of NGLY1, a regulator of NRF1 activation, attenuates NRF1 accumulation and increases cell death in cancer cells exposed to proteasome inhibitors." (PMID 33535386, 2021). "In particular, we focused on the role of NRF1 in cancer cells as a transducer of metabolic signals to induce transcription." (PMID 33535386, 2021). "Then, we introduce the NRF2 addiction of cancer cells, which confers unique features in terms of metabolism and epigenetic regulation, and the contribution of NRF1 to cancer malignancy, which is regulated by one of the oncometabolites, UDP-GlcNAc." (PMID 33535386, 2021). "In this review, we provide a brief overview of NRF2-mediated cancer malignancy and elaborate on NRF1-mediated drug resistance affected by an oncometabolite UDP-GlcNAc." (PMID 33535386, 2021). "As a master regulator of proteasome subunit genes, NRF1 is critical for the “proteasomal bounce back response”, which confers resistance to proteasome inhibitors on cancer cells." (PMID 33535386, 2021). "Our bioinformatic analysis shows solid evidence to propose oncogenic role of H2A.Z in CC, by regulating the expression of cancer-associated genes at promoter and enhancer levels, as well as its association with TFs such as RNA Pol II, NFYA, and NRF1." (PMID 35317119, 2021). "Since NRF1 maintains proteasome activity by inducing proteasome subunit genes in response to proteasome inhibitors, NRF1 protects cancer cells from proteotoxicity induced by anticancer proteasome inhibitors." (PMID 33535386, 2021). "The NRF1 ChIP-seq data from the ENCODE project confirms the binding of NRF1 to ATG5 and ATG7 promoter regions in 4 different cancer cells (HepG2, K562, SK-N-SH, and HeLa-S3 cell lines)." (PMID 34458153, 2021). "A close relationship between metabolism and proteostasis via NRF1 O-GlcNAcylation is a highly conserved defense mechanism among various species that is hijacked by cancer cells." (PMID 33535386, 2021). "Together, these results corroborate the rationale that Nrf1 acts as a bona fide dominant tumor repressor, by its intrinsic inhibition of Wnt/β-catenin signaling and relevant independent networks in cancer development and malignant progression." (PMID 32273945, 2020). "To determine the contribution of Nrf1 knockdown to distant metastasis of cancer in vivo, here, we injected the human shNrf1- or shNC-expressing HepG2 cells (2 × 106 in a solution of 200 μL) into nude mice through their tail veins." (PMID 32273945, 2020).
cancer (continued). "Nrf1 and Nrf2 are expressed across almost all tissues, whereas Nrf3 expression is predominantly placental and induced in several types of cancer cells such as colon adenocarcinoma." (PMID 32456207, 2020). "Collectively, these demonstrate that Nrf1 and Nrf2 play distinct and even opposite roles in mediating cancer cellular responses to the metabolic stress induced by glucose starvation." (PMID 32774674, 2020). "Collectively, these corroborate the rationale that Nrf1 acts as a bona fide dominant tumor repressor, by intrinsic inhibition of the Wnt/β-catenin and their independent signaling networks involved in cancer development, progression, and malignancy." (PMID 32273945, 2020). "From these results, we concluded that O-GlcNAcylation is required for the NRF1-dependent proteasome bounce-back response and that OGT inhibition sensitizes cancer cells to proteasome inhibitors by antagonizing NRF1 stabilization." (PMID 29941490, 2018). "Further calculation of the DEGs distribution unraveled that signal transduction, cancer-relevant, immune system and metabolism were the most abundant secondary KEGG pathways in Nrf1- or Nrf2-deficient cells." (PMID 30562963, 2018). "The crosstalk between mitochondria and nucleus mediated by transcription factors, such as NRF1, plays a significant role in the survival of cancer cells." (PMID 30486409, 2018). "Our present data suggest that NRF1 is also involved in the promotion of cell invasion and extracellular matrix remodelling, which are hallmarks of aggressive cancers, through its functional interactions with LSD1 and ERRα." (PMID 29968728, 2018). "This study has revealed a critical contribution of O-GlcNAcylation in cancer cells to maintaining proteasome activity via NRF1 protein stabilization." (PMID 29941490, 2018). "It was recently shown that the expression of NRF1 also increases in cancers and constitutes a factor of poor prognosis." (PMID 29968728, 2018). "However, the pathogenic role of NRF-1 in cancer cells remains unclear." (PMID 28993637, 2017). "TDP1 expression had a significant correlation with NRF-1 expression in the NCI-60 human-tumor cell-line panel as well as in the Cancer Cell Line Encyclopedia." (PMID 28993637, 2017). "Blocking the activation of proteasome subunit gene expression by Nrf1 has been proposed as a potential strategy to improve effectiveness of proteasome inhibitors in cancer treatment." (PMID 27528192, 2016). "These alterations in morphological phenotypes of between Nrf1α−/− and Nrf1+/+ cell lines have led us to suppose that Nrf1α-specific knockout enables the cells to undergo the putative EMT, a process entailing a risk of cancer transformation." (PMID 27065079, 2016). "The results demonstrated a gradient staining pattern of Nrf1 radially from the core carcinoma nodules towards the pericarcinoma tissues." (PMID 27065079, 2016). "The resulting images illustrated that the human carcinoma derived from Nrf1α−/− HEA157 cells was estimated in size to be ~3.0 times larger than that of the carcinoma derived from Nrf1+/+ HepG2 control cells." (PMID 27065079, 2016). "The survival curve demonstrated that a lower expression level of NRF1 leads to poor survival rate in cancer patients, which is at least partly due to the enhancement of radio-resistance characteristics in patients during radiotherapy." (PMID 26201446, 2015). "Despite the importance of Nrf1 in proteasome biology and its potential as an anti-cancer target, a thorough understanding of the molecular mechanism behind its activation is currently lacking." (PMID 24448410, 2014). "Previously, we demonstrated that in cancer cells, depletion of Nrf1 slows down recovery of proteasome activity upon transient inhibition of the proteasome and enhances apoptosis caused by a covalent proteasome inhibitor." (PMID 24448410, 2014). "The effect of NRF1 on the sensitivity of cancer cells to EZH2is is EZH2 dependent." (PMID 42140904, 2026).
cancer (continued). "Notably, we further found that the status of NRF1 expression affected the sensitivity of human cancer cells to EZH2is, including GSK343 and tazemetostat." (PMID 42140904, 2026). "Here, we report that the nuclear respiratory factor 1 gene (NRF1) is the gene whose expression is most strongly correlated with that of the EZH2 gene in various cancer cell lines and that changes in NRF1 expression consistently cause changes in EZH2 expression in cancer cells." (PMID 42140904, 2026). "However, cancer cells counteract this effect by activating an adaptive response through the transcription factor nuclear factor erythroid 2-related factor 1 (NRF1, also known as NFE2L1)." (PMID 42115609, 2026). "These early findings suggest that targeting NRF1 could enhance the effectiveness of conventional cancer treatments, positioning it as a promising focus for future therapeutic strategies." (PMID 41438988, 2025). "The co-regulation of the NatA and the proteasome complexes occurs in both cancer and non-cancer cells, with NRF1 potentially being the transcription factor underlying this connection." (PMID 38864963, 2025). "Therefore, in addition to being a crucial transcription factor, NRF1 has also emerged as a valuable biomarker for cancer diagnosis and prognosis." (PMID 38055835, 2024). "The roles of PGC-1α/NRF1/2/TFAM in human cancers are still under investigation." (PMID 39273403, 2024). "Furthermore, we confirmed that de novo methylation is precluded across cancers at CpGs lying in genomic regions enriched for TF binding signatures associated with SP1, CTCF, NRF1, GABPA, KLF9, and/or YY1." (PMID 35440061, 2022). "The PSMD14 inhibitor, capzimin (CZM), inhibits proteasome activity but differs from the 20S proteasome subunit-inhibiting bortezomib (Bz) in that it does not induce aggresome formation or Nrf1 upregulation, which underlie Bz resistance in cancer cells." (PMID 35269789, 2022). "Therefore, this study revealed that NRF1 promotes cancer cell growth via the indirect transcriptional activation of E2F1 and is a potential biomarker in LIHC." (PMID 35448958, 2022). "In the present study, we show that targeting PSMD14 may evade the mechanisms through which cancer cells acquire resistance to Bz, a PI targeting 20S proteasome CP, such as the aggresome formation and Nrf1 activation." (PMID 35269789, 2022). "This study shows that Nrf1 activation and aggresome formation, which underlie the PI resistance mechanisms of cancer cells, are not induced by PSMD14 inhibition." (PMID 35269789, 2022). "The mechanisms thought to confer PI resistance to cancer cells include the upregulation of Nrf1, a transcription factor that increases the expression of proteasome subunits, and the formation of aggresome, which allows cells to escape proteotoxicity by sequestering toxic cellular aggregates." (PMID 35269789, 2022). "However, increased double-positive NRF1 and NRF2 expression in cancer cells are associated with an improved probability of survival over five years." (PMID 36359002, 2022). "Many MYC binding motif-enriched genes are associated with E2F or NRF1 binding motifs, suggesting that NRF1 may orchestrate both MYC and E2F to regulate common target genes linked to various cancer." (PMID 35448958, 2022). "Higher CPEB3/NRF3 expression, but not higher CPEB3/NRF1 expression, is associated with poor prognosis of cancer patients." (PMID 34884489, 2021). "Interestingly, ChIP-seq data with NRF1 in 4 different cancer cell lines depicted strong enrichment in close proximity of both ATG7 and ATG5 TSSs." (PMID 34458153, 2021). "Conversely, NRF1 activity is under metabolic regulation in cancer cells." (PMID 33535386, 2021).
cancer (continued). "Another member of the CNC family, NRF1, plays a key role in the therapeutic resistance of cancers." (PMID 33535386, 2021). "In this review, we introduce the roles of NRF1 in the cancer malignancy in comparison with NRF2." (PMID 33535386, 2021). "Similarly, disruption of the TIP60 complex, which is required for NRF1 transcriptional activity, leads to the decreased viability of proteasome inhibitor-treated cancer cells." (PMID 33535386, 2021). "Focusing on NRF1, we consider that metabolism impacts proteostasis in cancer cells." (PMID 33535386, 2021). "If the NRF3 gene is deficient, NRF1 escapes from CPEB3-mediated translational repression, and complementarily plays a transcriptional role for the robust maintenance of basal proteasome activity in cancer cells." (PMID 34884489, 2021). "Cancer cells counteract the effects of proteasome inhibitor treatments by inducing proteasome gene expression (i.e., the proteasome bounce-back response), and both NRF1 and NRF3 mediate this response." (PMID 32962187, 2020). "Our work also demonstrated that cancer cells can be sensitized to PI-induced apoptosis when NRF1 is depleted, thereby establishing the notion that attenuation of the bounce-back response could improve the efficacy of PI-mediated cancer therapy." (PMID 31947743, 2020). "However, for this to be a viable strategy, demonstration is critical of the requirement of DDI2 and Nrf1 for this compensatory mechanism in actual human-cancer-patient samples." (PMID 32033280, 2020). "Of note, Nrf1 was shown to be essential for regulating glycolysis pathway, but it is unknown whether it plays a role in cancer metabolic reprogramming, particularly in response to glucose starvation." (PMID 32774674, 2020). "Recently, it was reported that Nrf1 stability is also regulated by O-linked N-acetylglucosamine (O-GlcNAc) modification in serine or threonine residues by the O-GlcNAc transferase (OGT), which is an enzyme that is highly active in many types of cancer." (PMID 32456207, 2020). "We reasoned that DDI2 depletion could sensitize these cancer cells to CFZ-induced apoptosis via inhibition of the NRF1-mediated bounce-back response." (PMID 31947743, 2020). "However, Tomm34 is transcriptionally regulated by NRF-1 and NRF-2 and these latter are implicated in directing metabolic reprogramming during stress and are often hyperactive in cancers." (PMID 30917858, 2019). "Furthermore, downstream signal-dependent transcription factors activated by PI3K/AKT/mTOR signaling, such as MYC and NRF1, stimulate transcription of cell proliferation and metabolic genes allowing cancer cell growth." (PMID 31315653, 2019). "A high NRF-1 protein level is linked to an increment in the transcription of nuclear genes encoding some subunits of several respiratory chain complexes and ATPS in cervix HeLa cancer cells." (PMID 31600993, 2019). "Thus, activation of Nrf1 in response to proteasome inhibition, constitutes a mechanism of resistance in cancer treatment." (PMID 31295808, 2019). "We next investigated whether enhancement of cellular O-GlcNAcylation increased the endogenous abundance of NRF1 protein, because metabolic reprogramming of cancer cells often supports high levels of O-GlcNAcylation (33, –, 36, 41)." (PMID 29941490, 2018). "Based on our previous studies, we determined whether NRF1 contributes to the generation of cancer stem cells during E2-induced cell transformation of breast epithelial cells." (PMID 30486409, 2018). "NRF1 has also been found misregulated in different carcinomas." (PMID 29119102, 2017). "Further comparisons of results measured from HCC samples #1, #5 and #7 revealed that expression of Nrf1 mRNA and its products (particularly of ~120-kDa Nrf1α) is significantly decreased in intermediately-differentiated carcinomas compared to its para-carcinoma tissue." (PMID 27065079, 2016).